SNORA36C (small nucleolar RNA, H/ACA box 36C)
Gene: Small nucleolar RNA gene on chromosome 2 (69,520,043 to 69,520,174, reverse strand). Ensembl gene ENSG00000207016.
Gene Ontology:
Biological process: RNA processing
Cellular component: nucleolus
Homologues: Orthologues: chimpanzee SNORA36C (100% identical), macaque SNORA36C (100% identical). Paralogues in human: SNORA36A (97% identical), SNORA36B (87% identical).